CCL19 (C-C motif chemokine ligand 19)
Diseases named in the same sentence as CCL19 in open-access papers (continued):
Sharing a sentence is not in itself a finding about the gene and the disease.
tumor (continued). "The combination treatment caused increased secretion of CCL2, CCL21, CXCL1, CXCL2, CXCL5, CXCL9 and CXCL16, whereas the levels of CCL11, CCL17, CCL19, CCL22, CCL25, CCL27 and CX3CL1, which are associated with protumourigenic effects, were decreased in the tumours." (PMID 33014356, 2020). "BCP also suppressed the number of lipid vacuoles and F4/80+ macrophage (MΦ) and macrophage mannose receptor (MMR)+ M2-MΦs in tumor tissues and adipose tissues surrounding the lymph nodes and reduced the CCL19 and CCL21 levels in the lymph node and CCR7 expression in the tumor." (PMID 32998300, 2020). "In addition to the effect on a cancer cell, the described axis CCL19/CCL21→CCR7 also affects the cellular composition of a tumor." (PMID 33076281, 2020). "Initial reports suggested that CCL21 and CCL19 were anti-tumorigenic, as they could attract lymphocytes that would attack the tumor." (PMID 32340161, 2020). "Analysis of the total thymic cell population suggests insignificant changes in CCL17 (ligand for CCR4) and a modest decrease in CCL19 (ligands for CCR7) at day 25 but a drastic reduction in expression of CCL21 (ligands for CCR7) when comparing thymi harvested from tumor-bearing vs. control mice." (PMID 32582141, 2020). "Because the same chemokines that recruit anti-tumor leukocytes can also recruit pro-tumor leukocytes (for example CCL19 and CCL21 recruit both Tregs, mDCs, and activated T cells), therapeutically targeting chemokines or chemokine receptors in cancer is complicated." (PMID 30873179, 2019). "However, another study that engineered “armored” mesothelin CAR T cells that constitutively expressed both the cytokine IL-7 and the chemokine CCL19 showed complete tumor regression and prolonged survival in a solid tumor mouse model." (PMID 30804938, 2019). "Importantly, anti-CD19-CAR and CCR7 conferred to NK cells an up to 5 fold increase in killing of CD19+ tumor cells and a 6 fold increase of migratory capability in response to CCL19 or CCL21, respectively." (PMID 31114587, 2019). "Our study confirmed that CCL19 low-expressed in CRC is able to promote tumor angiogenesis, indicating that CCL19 may be a promising therapeutic target in CRC anti-angiogenic treatment." (PMID 30250188, 2018). "Recent articles have indicated that the CCL19/CCR7 axis can promote tumor progression." (PMID 30250188, 2018). "In addition, we detected the association between CCL19 expression and tumor microvessel density (MVD) of CRC tissues, and the results showed that CCL19 levels were negatively correlated with angiogenesis." (PMID 30250188, 2018). "The effect of CCL19 on tumor angiogenesis remains to be studied further." (PMID 30250188, 2018). "We further investigated the role of CCR7 on CCL19-related tumor angiogenesis." (PMID 30250188, 2018). "Besides, CCL19 expression was positively correlated with the tumor diameter (p = 0.001) and TNM stage grouping (p = 0.001)." (PMID 29088748, 2017). "Next, we also detected the role of CCR7 in CCL19‐induced tumor migration and invasion." (PMID 28378417, 2017). "Furthermore, the expression of LT#βR-related chemokines, such as CCL21, CCL19 or CXCL13 increased in the EL4-Axl-tumor bearing mice compared to the mock control." (PMID 28423548, 2017). "PCR-based approaches, such as combining analyses of a combination of mature FDC markers, HEV markers and TLS associated chemokines such as CCL19, CCL21 and CXCL13, could also decrease the chance of missing TLS-positive tumours." (PMID 25177210, 2014). "Similar experiments were conducted by injecting tumor-bearing mice IM with pDNA encoding Her2/neu with or without CCL19 pDNA." (PMID 24967094, 2013). "The induction of CXCL9/CXCL9/MIG and CXCL10/CXCL10/IP-10 may be responsible in part for the tumour reduction following CCL19 administration." (PMID 16598185, 2006).
tumor (continued). "Because DCs are potent APCs that function as principal activators of T cells, CCL19's capacity to facilitate the colocalisation of both DC and T cells may reverse tumour-mediated immune suppression and orchestrate effective cell-mediated immune responses." (PMID 16598185, 2006). "Therefore, how to deliver CCL19 into the tumor to make it play a better function of tumor inhibition and reduce its toxic side effects could be a problem that needs to be addressed." (PMID 41446741, 2025). "CCR7, expressed in various lymphoid tissues, activates B and T lymphocytes and facilitates tumor cell migration by mediating interactions between tumor cells and chemokines CCL19/CCL21, and may enhance tumor cell anti-apoptotic capacity through regulation of necroptosis-related gene expression." (PMID 40547036, 2025). "Moreover, when CCR7 CD19 t-haNK cells injected into NSG mice inoculated with CCL19-secreting Raji lymphoma cells, tumor control and survival were increased in both local and systemic tumor models compared to mice treated with CD19 t-haNK cells that do not express the CCR7 receptor and control mice." (PMID 41246355, 2025). "TLSs supported by CCL19+ TRC‐like fibroblasts were closely associated with CD8+ T cells, and depletion of CCL19+ pulmonary fibroblasts led to enhanced tumor growth through dampened T cell immunity, suggesting TLSs specifically contribute to local CD8+ T cell‐mediated anti‐tumor immunity." (PMID 40884054, 2025). "The upregulation or downregulation of FTO-related genes may affect the expression of some relevant oncogenes in tumor cells by affecting mRNA methylation; for example, chemokine CCL19 expression is downregulated in tumor tissues after the knockdown of FTO genes." (PMID 38053093, 2023). "Moreover, “armored” CARs, co-expressing cytokines such as IL-12, IL-15, or IL-7/Chemokine (C-C motif) ligand 19 (CCL19), have demonstrated superior proliferative capacity, metabolic fitness, persistence, and anti-tumor efficacy compared to conventional CARs devoid of cytokine support." (PMID 37762648, 2023). "Among the 11 APC-binding molecules tested, CCL19 was selected for further characterization due to its ability to induce strong and balanced neoepitope-specific T-cell responses, and render complete tumor rejection in a prophylactic setting and partial tumor control in an early-therapeutic setup." (PMID 37720215, 2023). "Meanwhile, CCL21/CCL19 attract CCR7 + T cells as well as other immune cells and alter the ectopic lymph node structure associated with cancer prognosis by co-localizing synaptic cells and T cells, thereby promoting immune activity in the tumor microenvironment (TME) leading to immune infiltration." (PMID 37864213, 2023). "It is possible that in the case of non-advanced tumors, increased CCL19 mRNA expression level may be caused by the infiltration of immune cells at the tumor site during the first stage of antitumor immunological reaction." (PMID 35160116, 2022). "Additionally, the stimulation by CCL19 or CCL21 led to overexpression of CCR7 on the tumor cells and promoted cancer cell migration and infiltration into lymph nodes, which have been confirmed by the observation that increased CCR7 on cancer cell enhanced metastasis from breast to lung." (PMID 35359417, 2022). "After tumor recession, traceable quantities of CCL19 expression could be detected in serum in the mesoCAR-CCL19 group but not in the mesoCAR-N19 group, although the presence of CD3-positive T cells could be detected in peripheral blood by flow cytometry in both of these CAR-T groups." (PMID 35990619, 2022). "CCL19 secretion in the mesoCAR-CCL19 group was significantly higher compared with that in the mesoCAR-N19 group, which maybe because mesoCAR-N19 tended to be only activated in the tumor tissue site." (PMID 35990619, 2022).
tumor (continued). "Additionally, these researchers reported that the administration of CCL19-IL-7 CAR-Ts into mouse models also led to an increase in the number of other tumor-site trafficking immune cells alongside suppressing the expression of exhaustion markers (such as PD-1) on the endogenous T lymphocytes." (PMID 35634281, 2022). "Therefore, the study first verified whether overexpression of CCL19 by virus-infected tumor cells could recruit CAR-T cells." (PMID 34527749, 2021). "Therefore, generating effective CCL19 in tumor tissues may be one of the important factors to address lymph node homing of CAR-T cells in vivo." (PMID 34527749, 2021). "Therefore, elevated CCL19 expression could induce the function of T-zone reticular cells and recruit T cells and DCs to tumor tissues." (PMID 34544443, 2021). "Such an approach may be optimally tailored by choosing a chemokine ligand and receptor matching pair that overlaps with physiological chemokine ligand expression in specific tumours e.g. using CX3CL1/CX3CR1 matching in ovarian cancer or CCL-19/CCR7 matching in breast cancer." (PMID 29157300, 2017). "Divergent effects were observed for tumor Gleason score, with two genes being associated with a higher Gleason score (ITGAX; OR = 3.87 [1.88–7.56] and ZNF322; OR = 2.26 [1.27–4.02]) and two genes with a Gleason score <7 (CCL19; OR = 0.46 [0.24–0.88] and HIST1H1A; (OR = 0.45 [0.24–0.86])." (PMID 25411967, 2014). "However, the results of interaction between DCs and tumor cells could be multifaceted based on CCR7/CCL19 or CCR7/CCL21 interaction." (PMID 25110692, 2014). "Hence, an increase in IFN-γ at the tumour site of CCL19-treated mice could explain the relative increases in CXCL10/IP-10 and CXCL9/MIG." (PMID 16598185, 2006). "In addition, CCL19-treated tumour-bearing mice showed significant reductions in TGF-β at the tumour sites; TGF-β is an immune inhibitory cytokine that may potently suppress Ag and presentation, antagonise CTL generation and macrophage activation." (PMID 16598185, 2006). "Co-delivery of CCL19 pDNA and the PD-1/PD-L1 interaction inhibitor BMS-1 using RGD-modified nanocarriers targeting tumor integrins enhanced local antitumor immunity." (PMID 41745543, 2026). "Previous studies have shown that pantothenic acid and its derivatives can promote the proliferation and invasion of tumor cells through MAPK and NF‐κB pathways, while CCL19 can inhibit these pathways." (PMID 40898658, 2025). "C–C Motif Chemokine Ligand 19 (CCL19) is a chemokine, and its upregulation inhibits GC cell proliferation and tumor growth by upregulating the C–C Motif Chemokine Receptor 7 (CCR7)/AIM2 axis, while silencing AIM2 abrogates the effects of CCL19 on tumor growth." (PMID 41291696, 2025). "The results demonstrated a significant enhancement in the anti-tumor efficacy of CAR-T cells armed with IL-15 and CCL19, characterized by more robust and rapid tumor control." (PMID 40177238, 2025). "This signature, comprising CCL19, ICOSLG, IL11, PTGES, TNFAIP3, and TRAF3IP3, has been demonstrated to predict survival outcomes across a range of cancers and to correlate with tumor progression at the level of multi‐omics." (PMID 40714831, 2025). "They demonstrated that CAR T-cells armored with LIGHT upregulated expression of chemokines CCL19, CCL21, and CXCL13 in both stromal cells and tumor cells, enhancing the ability of the stromal cells to recruit T-cells in migration assays." (PMID 41019052, 2025). "For instance, cytokines such as IL-12 enhance T-cell activity, while chemokines like CCL19 and CCL21 promote dendritic cell migration to the tumor site." (PMID 39861713, 2025). "While a previous study introduced IL-15 and CCL19 into CAR-T cells and evaluated the anti-tumor effects using a zebrafish xenotransplantation model, mouse xenograft models remain the gold standard for preclinical evaluation of CAR-T cell therapy." (PMID 40177238, 2025).
tumor (continued). "Single cell analysis identified six major fibroblast subgroups; universal (PI16+) fibroblasts, ADH1B + fibroblasts and CCL19 + FRC-like fibroblasts were present in normal tissue and tumours." (PMID 39757146, 2025). "Several studies have shown that the CCL19/CCL21-CCR7 axis is crucial for promoting the infiltration of immune cells, including DCs and T cells, into tumor sites." (PMID 39861713, 2025). "Key immune activation and tumor suppression genes including CD2, CD3, CD247 (CD3 zeta chain), CD48, CD84, CCL19, CXCL10, and SLAMF6 were consistently upregulated in the hot phenotype across all ancestries." (PMID 41387728, 2025). "Four types of PSCs (CCL19+, ISG15+, PLXDC1+, and MYH11+) were identified as TPSCs with high RO/E scores in tumor tissues, while remained three PSC subclusters were identified as CPSCs, mainly in the control pancreas and persist in tumor tissues." (PMID 40091495, 2025). "Research indicates that tumor tissues expressed ligands for these receptors of chemokines, with the interactions of CXCL12‐CXCR4, CXCL10‐CXCR3, and CCL19 –CCR7 play crucial role in attracting CD8+ T cells to infiltrate tumors." (PMID 39727149, 2025). "CCL19 and CCL21 recruit naïve/central memory T cells to tumor tissue, allowing them to migrate from the HEVs into the TLS." (PMID 40038799, 2025). "The interaction between T follicular helper cells and B cells can promote immune-activated germinal center response, which further activates CCL19-21/CCR7 axis and CXCL13/CXCR5 axis and promotes tumor development 50-52." (PMID 39895788, 2025). "For stromal cells, we identified four mural cell subclusters (CCL19+ pericytes, RGS5+ pericytes, COL4A1+ smooth muscle cells [SMCs], and MYH11+ SMCs) and two EC subclusters (peripheral ECs and tumour core ECs)." (PMID 38943472, 2024). "In line with the idea that CCL19 supports immune surveillance, the administration of intratumoral CCL19 mobilized CD4+ and CD8+ T cells and DCs at the tumor." (PMID 38786066, 2024). "Together with the current result showing a skewed TCR clonality, it is suggested that IL7 and CCL19 produced by 7 × 19 CAR-T induce accumulation and proliferation of CAR-negative T cells expressing limited TCR with a reactivity to tumor antigens." (PMID 39240078, 2024). "Among these 23 TLSRGs, CCL19, CCL21 and IL1R2 were highly expressed in normal tissues, while the rest genes were highly expressed in tumor tissues." (PMID 39493749, 2024). "In summary, our findings shed light on the intra-tumor immune infiltration in HCC and underscore the role of DKK1+ tumor cells in hindering the infiltration of CCL19+ fibroblasts and plasma cells, thereby contributing to immune resistance." (PMID 39505867, 2024). "Findings have revealed that the introduction of CCL19 expression via AAV-CCL19 within tumor tissues facilitated the movement of memory T cells, such as memory CAR-T cells, into the core of the tumor." (PMID 38216938, 2024). "Tumor cells with high levels of FAT2 expression also show a significant upregulation of the chemokine genes, including CCL2, CCL3, CCL4, CCL19, CXCL10, and CXCL11, in lung adenocarcinoma tissues." (PMID 38303018, 2024). "CCR7 is expressed in both tumour and lymphoid tissues and activates B and T lymphocyte migration towards CCR7 ligands (CCL19 and CCL21)." (PMID 38762550, 2024). "For instance, engineered T-cells expressing higher levels of c-c motif chemokine ligand 19 (CCL19), a chemokine ligand, significantly improved CAR-T cell tumour infiltration and survival." (PMID 39726634, 2024). "Another strategy is to modify CAR-T cells with the expression of a chemokine receptor or chemokine (CCL19, CCL21) that guides the CAR-T cells to the tumor site." (PMID 38191529, 2024). "The new data demonstrate that DKK1 is highly expressed in the tumor area of immune-exclusion samples, with DCN+CCL19+ fibroblasts excluded from the tumor core." (PMID 39505867, 2024).
tumor (continued). "To validate this finding, we assessed the correlation between CCL19 and the fibroblast marker DCN, which reached 0.45 in the intra-tumor immune infiltration spots." (PMID 39505867, 2024). "Our observations revealed CD3D+ T cells accumulating in clusters within the tumor area and tumor boundary, with IGHG1+ plasma cells and CCL19+ fibroblasts scattered within these T cell clusters." (PMID 39505867, 2024). "This study demonstrated the characterization of intra-tumor infiltration patterns in HCC and identified DKK1+ tumor cells impeding the infiltration of CCL19+ fibroblasts and plasma cells into the tumor area that induced immunosuppressive TME." (PMID 39505867, 2024). "Upregulation of genes that encode for proteins known to increase T and B cell trafficking to tumors (CCL19, CXCL9), migration (MACF1) and tumor cell killing (GZMB) correlated with responses." (PMID 38519913, 2024). "We performed immunohistochemical staining of CD4, CD8, CCL19, Ki-67, and CD1C in serial sections of the same tumor tissue of BRCA patients." (PMID 36755259, 2023). "The addition of CCL19 and CCL21 increased the infiltration of endogenous dendritic cells, while CCL21 also showed inhibition of tumor angiogenesis." (PMID 38201551, 2023). "CCR7 with its ligands CCL21 and CCL19 regulates the apoptosis of CD8 + T cells and participates in the process of tumor microenvironment remodeling." (PMID 37864213, 2023). "After identification of 2,472 cells from 8 BRCA patients using single-cell SRP114962 cohort, we found that CCL19 was mainly expressed in CD8+ T cells, and CD8+ T cell highly cover the tumor." (PMID 37944262, 2023). "In multiple murine tumor models, intratumoral injection of CCL19 or CCL21 increases the numbers of tumor-infiltrating DCs and T cells, retards tumor growth, and prolongs the survival of tumor-bearing mice." (PMID 38008741, 2023). "For example, some of the cytokines (CCL19 and GROα) were variably expressed between different CAF lines ranging between 15 and 200× higher levels in the CAFs compared to tumor cells." (PMID 37423299, 2023). "CCL19 is significantly low-expressed in CRC tissues and positively related to highly tumor micro-vessel density." (PMID 37598287, 2023). "Performing flow cytometry on seven additional samples from patients with HPSCC verified that LAMP3+ DCs were present in the tumor and expressed higher PD-L1, CD83, and CCL19 levels than LAMP3– DCs." (PMID 37853464, 2023). "The levels of cytokines CCL21, eotaxin, CXCL1, CXCL2, CCL7, CCL19, and CCL25, which are capable of supporting tumor invasion, were reduced in CM from MSCs-TRAIL by 1.2, 1.3, 4-8, 3.4-1.3, 1.5, and 1.3 times, respectively (n = 3, ** p < 0.01)." (PMID 36661524, 2023). "Up-regulating the expression of CCL19 in tumors can inhibit its growth by effectively recruiting CCR7 + DC and IFN-γ + CD8 + T cells into tumor locations, which can be a powerful anti-tumor treatment combined with anti-PDL150." (PMID 38049474, 2023). "An even more extreme example is that dysregulation of CCL19, a homeostatic chemokine that interacts with CCR7 to play a crucial role in the development of lymphoid organs, showed both tumor-suppressive and oncogenic effects in cancer." (PMID 37198402, 2023). "In preclinical breast cancer studies, IL-7 is often combined with chemokines such as CCL19 and CCL21 to improve the chemotaxis of CAR T cells and other immune cells to the tumor site." (PMID 38201551, 2023). "Genetic modification of tumor antigen‐specific T cell receptor (TCR)‐T cells to produce IL‐7 and CCL19 also significantly enhanced the therapeutic efficacy in mouse models." (PMID 37031457, 2023). "CCL17, CCL19, and CCL22 have been shown to mediate DC trafficking between the tumor and draining lymph nodes while promoting the activation of tumor-specific T cells." (PMID 37532692, 2023).